CASP9 (caspase 9)
Diseases named in the same sentence as CASP9 in open-access papers (continued):
Sharing a sentence is not in itself a finding about the gene and the disease.
bladder cancer (continued). "In this study, a novel prognostic model for bladder cancer was constructed based on POLB, FASN, CASP9, VDAC2, and RHOT2, which provided preliminary references for the prognostic evaluation of bladder cancer and subsequent studies related to its diagnosis and treatment." (PMID 41427247, 2025). "In the T24 bladder cancer cell line, THP treatment significantly increased the expression of apoptosis-related proteins, such as BAX, cleaved caspase-3, caspase-8, and caspase-9, while the expression level of anti-apoptotic protein BCL-2 was inhibited." (PMID 37173953, 2023). "For example, in the bladder cancer cell line T24, CuE administered at 0.5–1 μM induced apoptosis and triggered up-regulation of Fas/CD95, truncated BID (t-BID), apoptosis-inducing factor (AIF), and sequential activation of caspase-8, caspase-9, and caspase-3." (PMID 25072848, 2014). "Thus, increased levels of caspase-9 and -3 activation appeared to correlate with mitochondria-dependent apoptosis in Tan-IIA-induced bladder cancer cell death." (PMID 25192287, 2014).
oral cancer (23 papers, 2004 to 2025). "For instance, TQ increases the apoptotic changes in oral cancer cells via activation of Caspase 9 in an LC3-II-dependent manner." (PMID 38532470, 2024). "Either intrinsic (caspase 9) or extrinsic (caspase 8) upstream signaling is upregulated in oral cancer cells." (PMID 38399445, 2024). "PAC is a powerful antiproliferative agent that can disrupt cell cycle progression and induce oral cancer cell apoptosis through caspase 3 and caspase 9 and by inducing oral cancer cell autophagy." (PMID 37367068, 2023). "UVC/SK2 showed higher caspase 8 and caspase 9 (+) counts in oral cancer cells (Ca9-22 and OC-2) than in single treatment." (PMID 35625933, 2022). "In this study we demonstrated that ginsenoside M1 induces the activation of two initiator caspases, caspase-8 and caspase-9 in human oral cancer cells." (PMID 33352689, 2020). "The mRNA expression of caspase-3, caspase-8 and caspase-9 in HSC-3 oral cancer cells were analyzed by RT-PCR and Western blot assays." (PMID 25951128, 2015). "A mechanism of the disruption of mitochondrial membrane potential activating caspase 9 and downstream caspase 3 and 8 was suggested to be attributed to apoptosis induction in human oral cancer lines by celecoxib derivatives." (PMID 23554697, 2011). "Notably, X-ray/SK2 treatment exhibited higher activated caspase 9 (+) (%) in oral cancer cells than in normal cells, i.e., 60.0%, 95.7% vs. 45.0% for Ca9-22, CAL 27 vs. S-G, respectively." (PMID 38398060, 2024). "Moreover, the expression of cyclin-D1, Bcl-2, and MMP-9 were upregulated and caspase-9 was downregulated, which are the key molecules involved in oral cancer cell proliferation, survival, invasion, and migration." (PMID 29996471, 2018). "The curcumin analog HO-3867 has been shown to activate caspase 3, caspase 8, caspase 9, and PARP via the JNK pathway, resulting in the apoptosis of human oral cancer cells." (PMID 40002335, 2025). "Mechanistically, apoptosis signalers such as pancaspase, caspases 8, caspase 9, and caspase 3 were activated by SK2 in oral cancer cells." (PMID 35268676, 2022). "Apaziquone treated OSCC cells showed increased activation of Caspase 9 and Caspase 3, and Poly (ADP ribose) polymerase (PARP) cleavage suggesting induction of apoptosis by apaziquone in oral cancer cells." (PMID 26208303, 2015). "Consistently, in HSC‐3 cells, HO‐3867 reduced the pro form of caspase 8, caspase 9, caspase 3 and PARP, and enhanced the active form of caspase 8, caspase 9, caspase 3 and PARP These results imply that HO‐3867 induces apoptotic pathway through caspase pathway in human oral cancer cells." (PMID 35191177, 2022). "Moreover, cyclin-D1, Bcl-2, and matrix metalloproteinase-9 (MMP-9) were upregulated, and caspase-9 was downregulated, suggesting that silencing of NGAL increases oral cancer cell proliferation, survival, and migration." (PMID 29996471, 2018).
Alzheimer disease (15 papers, 2012 to 2025). A progressive, neurodegenerative disease characterized by loss of function and death of nerve cells in several areas of the brain leading to loss of cognitive function such as memory and language. "Increased caspase-9 activity has also been implicated in Alzheimer’s disease, the most common cause of dementia in older adults, whose neuronal pathology features progressive accumulation of amyloid plaques, neurofibrillary tangles, and synaptic loss." (PMID 34305609, 2021). "In Alzheimer’s disease, caspase-8 and caspase-9 become colonized in the brain, resulting in mitochondrial dysfunction." (PMID 38542318, 2024). "An increased level of activated caspase 9 is observed in the hippocampus of Alzheimer’s disease patients." (PMID 38135855, 2024). "The Alzheimer disease pathway is the second-ranked signaling pathway, and 5 key targets, CASP9, APP, NOS2, NOS1 and PTGS2, are enriched in this pathway." (PMID 37904435, 2023). "Consequently, a deficiency of BDNF/TrkB results in the inhibition of PI3K/Akt survival signaling and the activation of Bax/caspase-9 mitochondrial apoptosis, which are key factors in the pathophysiology of Alzheimer’s disease." (PMID 40430064, 2025). "Similarly, another study reported that Lut treatment increased Bcl-2 expression while reducing levels of pro-apoptotic proteins, such as Bax, Cyt c, cleaved Caspase-3, and cleaved Caspase-9 in a model of Alzheimer’s disease-induced neuronal apoptosis." (PMID 40332364, 2025). "Analysis of post mortem tissue from Alzheimer's disease (AD) patients and AD models have shown, on one hand, increased ROS and elevated markers of oxidative stress, and on the other hand, the activation of caspase 3, caspase 8, and caspase 9 in sporadic AD." (PMID 34426760, 2021). "In addition, ATP6V1G3 and COX17 were found to be involved in the oxidative phosphorylation pathway, as well as CASP9 being involved in the Alzheimer's disease and Parkinson's disease." (PMID 33247215, 2020). "In addition, ATP6V1G3 and COX17 were upregulated in the oxidative phosphorylation pathway and CASP9 was downregulated in the Alzheimer's disease and Parkinson's disease pathways in CKD patients." (PMID 33247215, 2020). "Likewise, our previous study showed that dietary DHA-acylated AST diesters significantly attenuated cognitive disorders via decreasing the protein expression of Caspase 9, Caspase 3, and cleaved-Caspase 3 in the brain of mice with Alzheimer’s disease compared with unesterified AST." (PMID 34564161, 2021). "CASP9 and PTGS2 in neurodegeneration_multiple diseases, NOS1, NOS2 in Alzheimer disease pathway were identified as core targets." (PMID 37904435, 2023). "Among the proteins involved in the Alzheimer's disease and Parkinson's disease pathways, in addition to the fact that we already know that COX7B, COX6A2 and UQCRQ affect the function of mitochondria, downregulation of CASP9 is thought to lead to neurodegenerative diseases." (PMID 33247215, 2020). "If caspase 9 activation were solely an effect of caspase 8 and not oxidative stress, it would suggest that mitochondria and ROS have a negligible effect on neurons in Alzheimer’s disease, thereby implying that the mitochondrial theory of Alzheimer’s development is incorrect." (PMID 38135855, 2024).
viral infection (15 papers, 2011 to 2025). "MAVS, a mitochondrial antiviral signalling protein, triggers caspase-9 and caspase-3 activation, which leads to apoptosis during viral infection." (PMID 41157608, 2025). "MAVS, localized to mitochondria, activates caspase 9 and caspase 3, promoting apoptosis during viral infection." (PMID 41157608, 2025). "The precursors of caspase-3 and caspase-9 were present in decreased amounts, indicating the activation of caspase-3 and caspase-9, 48 hours after viral infection of Huh-7 cells compared with before viral infection." (PMID 22040050, 2011). "It will be interesting to elucidate the relationship between viral infection and caspase-9 activation, since virus-related cellular apoptosis has been demonstrated in some HIV infected patients, while caspase-9 activation is noted in chronic hepatitis C viral infection." (PMID 25370148, 2014). "We now speculate that the structure of two CARD domains containing RIG-I favoring interacting with caspase-9 upon high-dose 3p-RNA transfection, which is different from that upon low dose of 3p-RNA or common dose of virus infection." (PMID 23484008, 2013). "We also found the increased expression of Viperin in Casp9−/− MEF cells compared to WT cells after HSV-1 infection, which is consistent with previous studies showing that the apoptotic caspase deficiency augments the IFN response in basal or virus infection conditions." (PMID 39833169, 2025). "Indeed during viral infection inducible nitric oxide synthase (iNOS) activity was found to have an anti-apoptotic effect and NO increases survival of monocytes by influencing caspase-3 and caspase-9 activation." (PMID 23861899, 2013). "Bcl-xL cleavage has also been reported to result from different stimuli such as IL-3 withdrawal, virus infection, caspase-3-like proteases from an apoptotic CTLL-2 cell lysate, or the direct activation of caspase-9 by chemically induced dimerization." (PMID 33076337, 2020). "Vero E6 cells were pretreated with Z-IETD-FMK (caspase-8 inhibitor) or Z-LEHD-FMK (caspase-9 inhibitor) at concentrations of 50 and 100 μM or DMSO, followed by viral infection." (PMID 32090691, 2020). "Conversely, inhibitors targeting caspase-9, pan-caspases, NLRP3 inflammasome, and RIPK1 significantly suppressed NF-κB activation, suggesting that these pathways are involved in the negative regulation of NF-κB activation during IBV infection, as previously suggested for other viral infections." (PMID 40284946, 2025).
diabetes (14 papers, 2012 to 2023). "Combined with the reported increase in caspase-9 activation in diabetic retinas, these results support a common association between diabetes, caspase-9 activation, and increased susceptibility to ischemic cell death across different organ systems." (PMID 34305609, 2021). "Allium Sativum plays a role in the treatment of diabetes by enhancing the gene expression of caspase 3 and caspase 9, reducing IL-1β, IL-6, and TNF-α level and increasing IFN-γ in vitro and in vivo." (PMID 37240430, 2023). "Ang (1‐7) downregulates diabetes‐induced iNOS, caspase family members like cleaved caspase 3, cleaved caspase 8 and cleaved caspase 9 as well as Bax expression in the rat pancreas, which are key genes involved in cellular stress and apoptosis, aggravating diabetes progression." (PMID 34561952, 2021). "The protein levels of BCL-2, caspase-9, and caspase-8 were also assessed to examine whether diabetes induces apoptosis in the cochlea." (PMID 34445504, 2021). "It is believed that higher expression values for caspase-9 in this study in relation to caspase-3, are due to the fact that the animals are carriers of diabetes induced by alloxan and ethanol drinkers, since these values were found in diabetic and diabetic-alcoholic groups." (PMID 32901682, 2020). "QTL also significantly suppressed the diabetes-induced activation of the p65/NF-κB and ERK1/2/MAPK pathways, as well as caspase-9 and caspase-3 levels in liver tissues of diabetic mice." (PMID 27975068, 2016). "Since it is acknowledged that activation of caspase-9 triggers caspase-3, Ojo and Olorunsogo speculate that QUE administration would reduce excessive caspase-3 activity and thus down-regulate testicular death in diabetes." (PMID 36555696, 2022).
ischemia (14 papers, 2010 to 2025). A hypoperfusion of the BLOOD through an organ or tissue caused by a PATHOLOGIC CONSTRICTION or obstruction of its BLOOD VESSELS, or an absence of BLOOD CIRCULATION. "Following ischemia, activated Bax induces the upregulation of caspase-9 in the brain tissue, which leads to cleavage and activation of caspase-3, the key mediator of apoptosis." (PMID 36552554, 2022). "In hippocampal cultures subjected to ischemia, inhibitors of caspase-8, caspase-9, and p38 MAPK decreased caspase-3 activity to 95%, 94% and 108%, respectively." (PMID 30778709, 2019). "In the presence of caspase-8 and caspase-9 inhibitors (40 μM), the ischemia-induced LDH release was diminished to 212% and 220%, respectively." (PMID 30778709, 2019). "Our results showed that ischemic insult markedly increased the number of both caspase-3- and caspase-9-positive neurons in the hippocampal CA1 region 3 days after global ischemia." (PMID 20686690, 2010). "In turn, caspase-9 is activated by high glutamate levels, as occurs during ischemia." (PMID 29740323, 2018). "The function of Bax during ischemia has been well documented, and plays a crucial role in mitochondrial-dependent apoptosis (Bax, cytosolic Cyto C, activated caspase-9 and activated caspase-3) via inducing mitochondrial permeabilization and therefore the release of apoptogenic factors." (PMID 28272306, 2017). "A large number of studies have suggested that caspase-9 and caspase-3 are involved in the succession of myocardial infarction, also restriction of caspase-9 and caspase-3 can remarkably alleviate ischemia-induced myocardial apoptosis with heart function improvement." (PMID 29065851, 2017). "Since activation of caspase-9 by release of cytochrome-C from mitochondria plays a central role in ischemia-induced apoptosis, we looked at the potential interactions of IL-1Ra with caspase-9 and with caspases -3, -6, and -7, acting downstream caspase-9 activation in this cell death pathway." (PMID 23308180, 2013). "The intrinsic pathway of apoptosis is triggered by various internal cellular stressors such as nutrient or oxygen depletion from ischemia and results in mitochondrial release of cytochrome c, formation of the apoptosome, and activation of executioner caspase-3 and caspase-7 by initiator caspase-9." (PMID 39000490, 2024). "When stimulated by ischemia, CYT-C translocates from the mitochondria to the cytoplasm, where it binds to Apaf-1, recruits caspase-9 to form apoptotic bodies, activates caspase-3, and promotes apoptosis." (PMID 40703757, 2025). "The decrease of caspase-9 and -3 activity was significant between cardiomyocytes treated with and without zVAD during ischemia, while there were no obvious changes when AKT2 was inhibited." (PMID 28272306, 2017).
non-small cell lung carcinoma (14 papers, 2013 to 2025). A group of at least three distinct histological types of lung cancer, including non-small cell squamous cell carcinoma, adenocarcinoma, and large cell carcinoma. "In non-small cell lung cancer zerumbone has been demonstrated to induce apoptosis through loss of mitochondrial membrane potential, release of cytochrome c, caspase-9 and caspase-3 activation and increased ROS production." (PMID 35931788, 2023). "The induction of cell cycle arrest and upregulation of apoptosis-related proteins Bax and caspase-9 by Taraxasterol can facilitate apoptosis in non-small cell lung cancer." (PMID 38297292, 2024). "SRSF1 regulates the AS of caspase 9 and then influences the chemosensitivity of non-small cell lung cancer (NSCLC)." (PMID 33495408, 2021). "In non-small cell lung cancer (NSCLC), there is a high expression of caspase-9b, an alternatively spliced short isoform of caspase-9." (PMID 39625520, 2024). "Down regulation of caspase-9 promotes proliferative, invasive, and migrative properties during high signaling of MAPK leading to poor prognosis in non-small cell lung cancer." (PMID 38027599, 2023). "For example, some studies demonstrate that PINK1 depletion in the non-small cell lung cancer (NSCLC) A549 cell line via shRNA reduced cancer cell proliferation, increased cell death, decreased ATP production, inhibited mitophagy, and increased ROS levels and caspase-9-dependent apoptosis." (PMID 40565152, 2025).
lymphoma (12 papers, 2003 to 2025). A malignant (clonal) proliferation of B- lymphocytes or T- lymphocytes which involves the lymph nodes, bone marrow and/or extranodal sites. "By this means, the impact of loss of both caspase-9 alleles on c-myc-induced lymphoma development could be measured in vivo." (PMID 24281211, 2010). "Caspase-9 deficiency and Apaf-1 deficiency were also incorporated into lymphoma model." (PMID 20145726, 2010). "Significant increases in activated caspase 3, caspase 8, and caspase 9 activities were observed in lymphoma cells as compared to controls after 48 h of treatment with hypoxic and normoxic hWJSC-CM." (PMID 32377203, 2020). "The percentages of lymphoma cells that were positive for activated caspase 9 activities were hWJSC-CM (21% O2): 27.8 ± 1.37%, hWJSC-CM (10% O2): 26.0 ± 1.08%, hWJSC-CM (5% O2): 36.3 ± 0.9%, and control: 13.8 ± 0.50%." (PMID 32377203, 2020). "This evidence point to a role of Caspase-9 (Casp-9) as the initiator caspase able to trigger Caspase-3 (Casp-3) cleavage following RSV treatment also in lymphoma cells." (PMID 24658441, 2014). "In order to examine the effect of Caspase-9 inhibition on T cell death and lymphoma formation in vivo, transgenic mice were generated using the Lck promoter that directs expression in mature and immature T cells." (PMID 21611191, 2011). "A previous study observed that DMSO could induce apoptosis in murine lymphoma cells through mitochondrial dysfunction and caspase-9 and -3 activation." (PMID 22529897, 2012). "Against expectation, loss of caspase-9 did not influence lymphoma development and the severity of disease." (PMID 24281211, 2010).